PIK3CA (phosphatidylinositol-4,5-bisphosphate 3-kinase catalytic subunit alpha)
Diseases named in the same sentence as PIK3CA in open-access papers (continued):
Sharing a sentence is not in itself a finding about the gene and the disease.
thyroid cancer (continued). "Little is known about the role of polymorphism of the PIK3CA gene in the development of thyroid cancer." (PMID 23185308, 2012). "Amplification and mutations in PIK3CA gene have been reported in many human cancers, including thyroid cancer, especially in follicular thyroid carcinoma and undifferentiated thyroid carcinoma." (PMID 23259526, 2012). "The genomic copy gain of PIK3CA gene is functionally important as it is associated with robust expression of the PIK3CA protein in thyroid cancer." (PMID 23185308, 2012). "Amplifications and mutations in PIK3CA gene have been reported in many human cancer types, including thyroid cancer." (PMID 20804548, 2010). "Over the past several years, the frequency of PIK3CA mutations and gene amplification has been analyzed in some sporadic thyroid carcinomas." (PMID 20804548, 2010). "The MAPK1, HRAS, and PIK3CA genes are associated with distinct thyroid cancer subtypes, suggesting the intriguing hypothesis that the unobserved latent factors are germline or somatic changes in these genes themselves." (PMID 39677786, 2024). "The prevalence of PIK3CA mutations differs among various types of thyroid cancer." (PMID 38313845, 2023). "Additionally, in cooperation with KRAS mutations, PIK3CA mutations were reported to be associated with metastasis in thyroid cancer." (PMID 31905960, 2019). "PTEN is downregulated in ~37% of well-differentiated thyroid carcinomas and downregulated or lost in >50% of highly malignant thyroid cancers; point mutations or copy number changes in PIK3CA are found in ~23% of anaplastic thyroid cancers where they can coexist with either RAS or BRAF mutations." (PMID 22927847, 2012). "Mutations and amplification of PIK3CA gene are characteristic for thyroid cancer, as well." (PMID 20804548, 2010). "This distribution of PIK3CA mutations among thyroid cancer subtypes may raise the valid possibility of it playing a role towards more aggressive cancer development, mirroring the different natural history of anaplastic (most aggressive) vs. papillary thyroid cancer (least aggressive)." (PMID 31905960, 2019). "PIK3CA and PTEN mutations are believed to have a driver role in 15 or more cancer types but are generally rare in thyroid cancer." (PMID 40226091, 2025). "Mutations in PIK3CA, AKT1, and PTEN have been associated with aggressive, radioactive iodine-refractory thyroid tumors and are typically late events in thyroid cancer pathogenesis." (PMID 40149275, 2025). "Mutations in the PI3K/AKT/mTOR pathway, including PIK3CA, AKT1 and PTEN are infrequent in thyroid cancer, though they can act as early driver mutations in certain RAS-like subtypes." (PMID 39926346, 2025). "PIK3CA activation in thyroid cancer can occur through multiple mechanisms, including activating mutations, gene amplification, and upstream activation by RAS mutations or PTEN loss." (PMID 40363930, 2025). "These inhibitors are currently being investigated for treating advanced thyroid cancers with PIK3CA alterations." (PMID 40363930, 2025). "In thyroid cancer, PI3K–PTEN–AKT dysregulation is mostly due to PTEN loss-of-function or to activating PIK3CA mutations, typically found in advanced and aggressive thyroid tumors." (PMID 41175860, 2025). "The current research about the incidence, metastasis, and prognosis of thyroid cancer indicated that PIK3CA, PTEN, CDKN1B, TSHR, and EIF1AX were also involved, which should be considered in the multi-gene panel." (PMID 39600648, 2024).
thyroid cancer (continued). "Other genetic mutations reported in various thyroid cancer include RAS PIK3CA, AKT1, PTEN, mTOR, and chromosomal rearrangements involving RET/PTC and PAX8-PPARɣ genes." (PMID 39724083, 2024). "In other types of thyroid cancers, most poorly differentiated thyroid carcinomas, mutations in other genes in the PIK3/AKT pathway, including PIK3CA, PTEN, and AKT, have been described." (PMID 36980552, 2023). "For thyroid cancer the author found an interaction between BRAF and PIK3CA mutations which has been previously reported." (PMID 36275468, 2022). "MAPK and PI3K/AKT pathways are dependent on activity of mutually exclusive RAS, BRAF and RET/PTC point mutations (BRAF/RAS/PIK3CA) and rearrangements (RET/PTC and TRK) which drive thyroid cancer oncogenesis." (PMID 34062862, 2021). "Specially, PIK3CA gene had 365 and 283 driver mutations in breast invasive carcinoma (BRCA) and thyroid cancer (THCA), respectively." (PMID 33179738, 2021). "As in AKT1, genetic alterations in PIK3CA appear late during malignant progression of thyroid cancer and are more common in ATC than DTC." (PMID 32751138, 2020). "Here, we studied mutations in the major genes (LPAR4, PIK3CA, and PTEN) of the GPCR-mediated PI3K pathway in a large series of pediatric and adult DTCs, and in aggressive thyroid cancer (PDTC and ATC) samples (n = 323) from a Saudi Arab population." (PMID 31289610, 2019). "Patients bearing PIK3CA mutations showed a significant poor overall survival (p = 0.0289) compared with people bearing wild-type PIK3CA suggesting the important role of this gene in aggressive thyroid cancer." (PMID 31289610, 2019). "Although somatic mutations of PIK3CA and PTEN genes have previously been documented in sporadic thyroid cancers, they were mostly observed in high-grade tumors of FTCs and ATCs." (PMID 31289610, 2019). "To test this, we chose thyroid cancer cell lines containing mutations in the commonly mutated oncogenes; BRAF, RAS, and PIK3CA, along with two cell lines sensitive to dasatinib; the BRAF mutant, BCPAP, and the RAS-mutant, Cal6210." (PMID 29487290, 2018). "Mutations in the RAS, PIK3CA, and PTEN genes in the PI3K pathway are the main genetic driving force of this pathway in human cancers, including thyroid cancers, particularly FTC and ATC." (PMID 26472282, 2015). "We previously found common genetic amplifications of the PIK3CA gene in thyroid cancer, which was confirmed in several later studies." (PMID 23185308, 2012). "This provides an explanation for the reciprocal relationship of rs17849071G/T with FTC, since PIK3CA amplification is an important oncogenic mechanism in thyroid cancer, particularly FTC." (PMID 23185308, 2012). "Previous genetic studies on the PIK3CA gene in thyroid cancer have been mostly focused on somatic oncogenic genetic alterations, such as activating mutations and genomic amplification." (PMID 23185308, 2012). "Thyroid carcinomas also show mutations in PI3K signaling effectors such as PTEN and phosphoinositide-3-kinase, catalytic, alpha polypeptide (PIK3CA)." (PMID 22927847, 2012). "The definite role of PIK3CA in multi-step carcinogenesis and acquisition of invasive capacity of thyroid cancers remains to be determined." (PMID 20804548, 2010). "Several studies have explored the PI3K–PTEN–AKT pathway as target for molecular therapy: double mutant BRAF p.V600E and PIK3CA thyroid carcinoma cells lines and xenograft models have heightened sensitivity to combination therapy with simultaneous MAPK and PI3K–PTEN-AKT pharmacological inhibition." (PMID 41175860, 2025). "In specific, PIK3CA and PTEN are the two most frequently mutated genes in thyroid cancer." (PMID 38672636, 2024).
thyroid cancer (continued). "Moreover, in cribriform morular thyroid carcinoma, other genetic alterations have been reported, including RET/PTC rearrangements, PIK3CA mutations, and RAS gene mutations." (PMID 38835742, 2024). "Somatic mutations in RAS, PIK3CA, KMT2C, and/or BRAFV600E, as well as somatic RET/PTC rearrangements could act as a somatic “second-hit” in the development of other forms of thyroid cancers in affected individuals." (PMID 33495912, 2021). "In another study, the integrative analysis of aggressive thyroid carcinomas, including ATC and advanced DTC, revealed the frequent presence of TERT, AKT1, PIK3CA, and EIF1AX mutations in combination with BRAFV600E and RAS mutations in these advanced forms of thyroid cancers." (PMID 32751138, 2020). "Another study reported that there is no involvement of PIK3CA mutations in pediatric thyroid cancer." (PMID 31905960, 2019). "The proto-oncogene PIK3CA has been well studied for its activating mutations and genomic amplifications but not single nucleotide polymorphism (SNP) in thyroid cancer." (PMID 23185308, 2012). "Thyroid cancers frequently harbor activating mutations in the mitogen-activated protein kinase (MAPK) and phosphatidylinositol 3-kinase (PI3K)/Akt signaling pathways, as represented by RET/PTC, RAS and BRAF mutations in the former and by PIK3CA and PTEN mutations in the latter." (PMID 24137342, 2013). "As PIK3CA amplification plays a prominent role in the tumorigenesis of thyroid cancer, particularly FTC, the significant decrease in the occurrence of PIK3CA amplification in association with rs17849071G/T may conceivably result in decreased development of FTC in the presence of this SNP." (PMID 23185308, 2012). "Genomic events were found in the thyroid cancer, MAPK via RAS signaling, and PIK3CA/AKT signaling pathways in 13 patients." (PMID 37932340, 2023). "Thyroid cancer is known to affect the MAPK and PIK3CA/AKT pathways, which contribute to cell proliferation and growth through the RAS signaling pathway." (PMID 37932340, 2023). "Four cases harbored gene fusions, including two cases harboring the TBL1XR1::PIK3CA fusion that has never been reported in thyroid cancer, so far." (PMID 41123735, 2025). "PIK3CA (Phosphatidylinositol-4,5-Bisphosphate 3-Kinase Catalytic Subunit Alpha) is a key component of the PI3K/AKT/mTOR signaling pathway, which is frequently dysregulated in thyroid cancer." (PMID 40363930, 2025). "More interestingly, two cases harbored the TBL1XR1::PIK3CA fusion, a molecular alteration never described in thyroid cancer, so far." (PMID 41123735, 2025). "Importantly, some classical oncogenes, such as PIK3CA, TWIST1, HER2, and HER3 were identified as the direct targets of ETS factors in thyroid cancer." (PMID 34221969, 2021). "Sanger sequencing of primary and metastatic tissues ruled out the presence of any mutations in known thyroid-cancer–related genes (H-, K-, N-RAS, BRAF, PTEN, PIK3CA), and PAX8-PPARG fusions were excluded by RT-PCR." (PMID 32674319, 2020).
thyroid cancer (continued). "Each PIK3CA and PTEN genes harbored somatic mutations in 7% (8/117) of aggressive thyroid cancers (PDTCs and ATCs) while no mutation was found in LPAR4 gene." (PMID 31289610, 2019). "We also found no mutation in the LPAR4, PIK3CA and PTEN genes of the 13 cases of PDTCs and ATCs (aggressive thyroid cancers)." (PMID 31289610, 2019). "Therefore, we examined the efficacy of the combination therapy across a panel of thyroid cancer cell lines representing common oncogenic drivers (BRAF, RAS, and PIK3CA)." (PMID 29487290, 2018). "Interestingly in support of this, the majority of PIK3CA-mutant thyroid cancer cell lines tested did not exhibit an increase in apoptosis in response to combined inhibition of Src and the MAPK pathway." (PMID 29487290, 2018). "In one study it is seen that PIK3CA mutation is not common rather its amplification is common and may be mechanism in activation of PIK3/akt in some thyroid cancer." (PMID 23768168, 2013).
meningioma (66 papers, 2014 to 2026). A generally slow growing tumor attached to the dura mater. "Research has also suggested that progestin-related meningiomas have higher rates of mutations in the PIK3CA gene." (PMID 40710211, 2025). "A recent review on PIK3CA‐mutated meningiomas underscores that a subset of these tumors, particularly those with non‐NF2 mutations, exhibit estrogen and progesterone receptor positivity and respond aberrantly to hormonal exposure via PIK3CA pathway activation." (PMID 41031251, 2025). "Several different PIK3CA activating mutations have been identified in meningioma and other tumors, with H1047R and E542K/E545K as the two most common mutation ‘hotspots’." (PMID 38571886, 2024). "Variants typical for angiomatous (brain) meningioma are PIK3CA, KIT, PTPN11, CDH1, SMAD4, and SMARCB1; the variants typical for psammomatous meningioma are APC, FGFR2, HNF1A, STK11, and JAK3." (PMID 38476782, 2024). "PIK3CA mutations occur in about 7% of all meningiomas; they are mutually exclusive with NF2 and AKT1 and often associated with TRAF7 mutations." (PMID 38137885, 2023). "Although initially suggested to be indicative of tumor progression, PIK3CA mutations are also found in low grade meningiomas." (PMID 38259646, 2023). "Only one patient (case #4) harbored a germline BAP1 mutation in both intracranial and distant meningioma manifestations, with an additional PIK3CA mutation." (PMID 36641486, 2023). "In a study assessing 55 meningioma patient samples, PIK3CA mutations were found in two patients who had atypical and anaplastic meningiomas respectively." (PMID 36686824, 2022). "Alpelisib, also known as BYL719, is a selective inhibitor of the constitutively activated PI3Kα product of PIK3CA in response to either of two hot spot mutations: p.His1047Arg or p.Glu545Lys, both of which present in few meningiomas." (PMID 36139608, 2022). "Based on these molecular features, several clinical trials in NF-2 wild type meningiomas, including targeted therapy for actionable mutations in PIK3CA, SMO, and AKT1 are ongoing (NCT02523014)." (PMID 33611710, 2021). "PIK3CA mutations are found in 4–7% of meningiomas and often cooccur with TRAF7 mutations but are exclusive of NF2, AKT1, and SMO mutations." (PMID 33801089, 2021). "In both studies, AKT1 and PIK3CA mutated meningiomas were primarily located along the midline anterior skull base including olfactory groove, tuberculum sellae, anterior clinoid, and medial sphenoid wing." (PMID 33346248, 2020). "It is important to note that AKT1 and SMO mutations are selectively observed in a subset of non-NF2-mutated meningiomas (9% and 6% of cases, respectively); furthermore, PIK3CA mutations occurred in 7% of non-NF2-mutant meningiomas." (PMID 30279357, 2018). "Next-generation sequencing has characterized recurrent somatic mutations in NF2, TRAF7, KLF4, AKT1, SMO, and PIK3CA, which are collectively present in ~80% of sporadic meningiomas." (PMID 27458586, 2016). "Oncogenic mutations in PIK3CA are observed in ~7% of non-NF2-mutant meningiomas, and occur mutually exclusive of AKT1 and SMO mutations, although they frequently co-occur with TRAF7 mutations." (PMID 27458586, 2016). "In meningiomas, these gene mutations have previously been shown to occur with a frequency similar to the PIK3CA mutations." (PMID 24932282, 2014). "The occurrence of the PIK3CA mutations in meningiomas was investigated in a previous study, and one of the patients with anaplastic meningioma was identified as a mutation carrier." (PMID 24932282, 2014). "In addition, also mutations of the gene encoding for the PI3K catalytic subunit alpha (PIK3CA) have been found in about 7% of non-NF2-altered meningiomas." (PMID 36181606, 2023). "In 2016, mutations in PIK3CA were found to be frequent drivers of certain meningiomas." (PMID 35712491, 2022). "Moreover, some actionable mutations, including SMO, AKT1, and PIK3CA, regulate meningioma growth and are under investigation in clinical trials." (PMID 35565385, 2022).